ALB (albumin)
Diseases named in the same sentence as ALB in open-access papers (continued):
Sharing a sentence is not in itself a finding about the gene and the disease.
cancer (continued). "The systemic inflammation score (SIS), based on the serum albumin level and LMR, has shown a better predictive effect on the prognosis of cancer compared to the single index." (PMID 32211311, 2020). "In the future, the potential cancer-specific predictability of other prognostic nutritional scores such as the GPS, CONUT, and PNI, which consider albumin and other immune-nutritional factors, should be validated." (PMID 32595832, 2020). "Recurrent somatic events were identified in the 3′ UTRs of TOB1 (carcinoma and pan-cancer meta-cohorts), NFKBIZ (lymphomas) and ALB (liver cancer)." (PMID 32025015, 2020). "Certain nanotherapeutics such as liposomal doxorubicin and PTX-loaded human serum albumin nanoaggregates are Food and Drug Administration (FDA)-approved cancer nanotherapeutics." (PMID 32075239, 2020). "Several nutritional markers, including ALB, BMI, PNI and NRI have been developed and used to assess the nutritional status of the cancer patients." (PMID 32087695, 2020). "Therefore, low albumin and high haemoglobulin may decrease the survival of cancer patients." (PMID 32232040, 2020). "In many cancer patients, as CRP increases, albumin continues to decline and albumin reflects systemic inflammation and nutritional status." (PMID 33299415, 2020). "Albumin and common laboratory tests for inflammation (e.g. CRP and white cell counts) are useful as predictors of prognosis in people with cancer e.g. Glasgow Prognostic Score." (PMID 32366995, 2020). "Thus, it would be helpful to understand whether the hypoalbuminemia is caused by cancer cells themselves or not, which would give another perspective on administrating fractionated albumin." (PMID 32368865, 2020). "Abraxane is a nanoparticle composite of paclitaxel (PTX) and human serum albumin (HSA), approved for cancer." (PMID 32971733, 2020). "The Glasgow Prognostic Score (GPS), which is based on serum albumin and C-reactive protein (CRP) levels, represents one of the most commonly investigated scoring systems usable for several types of cancer." (PMID 31936329, 2020). "We assessed the value of ratio indexes derived from serum albumin, prealbumin, and fibrinogen—AFR and FPR—as prognostic markers for human cancers in this updated meta-analysis." (PMID 31931816, 2020). "Recent studies have examined the albumin-fibrinogen ratio (AFR) and/or the fibrinogen-prealbumin ratio (FPR) as prognostic indicators in cancer." (PMID 31931816, 2020). "In addition, ALB could be used to predict the prognosis of cancer patients." (PMID 32280684, 2020). "Second, the BMI, ALB, and NLR, which are components of the ALI, seem to have better prognostic value in advanced stages of cancer." (PMID 31677642, 2019). "The present systematic review shows low SMI and low SMD to be consistently associated with measures of systemic inflammatory response, including CRP, albumin, mGPS and NLR, in patients with cancer." (PMID 31487957, 2019). "Our findings demonstrate that the SOD3-mimetic activity of an extracellular albumin-based macromolecular nitroxide, PNA, converts cancer cells from a tumorigenic state to a cytostatic state by reducing superoxide and ROS levels." (PMID 30941174, 2019). "In this review, we will focus on the recent advances in albumin nanovector (ANV) generation, providing insights into the synthetic processes, delivery properties, and applications in the treatment or diagnosis of cancer." (PMID 31195727, 2019). "Based on the combination of serum CRP and serum albumin, the GPS is a well-established, cheap and readily available tool for prognostic assessment in cancer patients." (PMID 30535923, 2019). "Here in, we used albumin-stabilized gold nanoclusters modified with doxorubicin and SN38 (AuNCs-DS) as combined therapy for cancer." (PMID 31295963, 2019). "Biomarkers of the systemic inflammatory response (albumin and CRP combined in the modified Glasgow prognostic score (mGPS)) predict survival in cancers with an established site." (PMID 31591445, 2019).
cancer (continued). "With albumin as the carrier, PNA is distributed in the intravascular and lymph compartments to intercept metastasizing cancer cells." (PMID 30941174, 2019). "Overweight or obese dogs had more aggressive carcinomas and higher triglyceride (p = 0.0363), VLDL (p = 0.0181), albumin (p = 0.0188), globulin (p = 0.0145) and lactate (p = 0.0255) concentrations." (PMID 31703601, 2019). "Even though cancer patients were excluded, the AUC of CRP/albumin ratio was higher than that of CRP for mortality in critically ill patients (0.585 vs. 0.559, p < 0.001)." (PMID 30297655, 2018). "In our study, age, serum albumin, total bilirubin, Cr., and INR level during initial admission course were surrogates for prognosis in non-cancer ESLD patients." (PMID 30240398, 2018). "We also investigated the impact of GPS, an inflammation-based cancer prognostic factor calculated from the values of CRP and albumin, on MPV and LMR." (PMID 30192878, 2018). "Therefore, preoperative serum albumin could serve as a good predictor of the prognosis of cancers." (PMID 29685957, 2018). "Another study showed that pretreatment albumin level was one of the independent predictors of DFS, cancer-specific survival and OS." (PMID 29576961, 2018). "The albumin and HDL levels were significantly lower and the triglyceride, VLDL and CRP levels were significantly higher in cancer patients compared with control patients (p < 0.05)." (PMID 29941786, 2018). "Therefore, the AGR takes the serum albumin and globulin levels into account concurrently, may more precisely mirror the body’s nutritional and inflammatory states and may be particularly helpful to predict the prognosis of cancer patients." (PMID 29300750, 2018). "Additionally, albumin has been identified as an important marker to aid in cancer control through stabilization of cell growth and DNA replication, and it serves as a versatile factor for multiple antioxidants and even protects against sex hormone-induced cancers." (PMID 29268783, 2017). "Certain systemic inflammation markers such as CRP, WBC, albumin, NLR, and platelet count have been confirmed to be poor prognostic factors in many cancer types." (PMID 28076369, 2017). "The correlation between albumin and LOS applied to most of the classes of diagnosis identified: malignant tumor, infections, bleeding conditions, fractures, pregnancy/childbirth and miscellaneous conditions (Others)." (PMID 28344803, 2017). "The results of this study confirm that defining the ECOG-PS and cancer stage, as well as measurements of LDH, albumin, and HGS, are of prognostic value for patients with surgical oncologic emergencies with respect to 30- and 90-day mortality." (PMID 26553441, 2016). "CRP and albumin as acute-phase proteins, which constitute the GPS score, are sensitive and reliable markers that reflect the systemic-inflammatory response in cancer patients." (PMID 27149487, 2016). "Human serum albumin nanoparticles (HSA-NPs) are widely-used drug delivery systems with applications in various diseases, like cancer." (PMID 28335244, 2016). "By combining the CRP and albumin values, which have both been reported to be independent prognostic factors for various types of cancer, the CRP/ALB ratio is believed to be a more useful marker." (PMID 27812440, 2016). "Potential hematological biomarkers representing SIR in cancer patients include C-reactive protein (CRP), albumin, Glasgow Prognostic Score (GPS), modified GPS (mGPS), and neutrophil-to-lymphocyte ratio (NLR)." (PMID 26880857, 2016). "The HSA based formulation that was the paclitaxel (PTX) albumin nanoparticles solution (ABRAXANE) developed by American bioscience has been approved by the Food and Drug Administration (FDA) for clinical cancer therapy." (PMID 26075280, 2015). "Cancer increased liver STAT-3 phosphorylation approximately 2-fold, which coincided with a significant 20% reduction (p = 0.002) in liver albumin protein concentration." (PMID 25789991, 2015).
cancer (continued). "There is now good evidence that markers of the systemic inflammatory response, namely C-reactive protein and albumin using standard thresholds (termed the Glasgow Prognostic Score, GPS) have independent prognostic value in patients with a variety of cancers." (PMID 25730322, 2015). "Preoperative albumin-globulin ratio (AGR) reflects both malnutrition and systemic inflammation in cancer patients." (PMID 26681341, 2015). "Albumin and gelatin are the proteins with more relevance for the preparation of DDS for cancer therapy." (PMID 26605001, 2015). "Previous studies identified the preoperative albumin to globulin ratio (AGR) as a simple and useful predictive biomarker for evaluation of prognosis in several cancers." (PMID 26681341, 2015). "Abraxane is a 130 nm albumin-bound particle form of paclitaxel (PTX), which is a member of the taxane family and an important agent in cancer chemotherapy." (PMID 26182353, 2015). "In recent years, albumin-based nanoparticles have been prepared and tested as DDS in different types of cancer." (PMID 26605001, 2015). "As a secondary aim, we also wanted to investigate if there was an association between 25OHD levels and survival time and compare with the well-established markers albumin and CRP, often used in clinical practice to estimate survival time in cancer patients." (PMID 26018761, 2015). "Since the initial work, a decade ago the combination of C-reactive protein and albumin, the Glasgow Prognostic Score (GPS/mGPS), has been shown to have independent prognostic value in more than 60 studies (>30,000 patients with cancer)." (PMID 26316945, 2014). "The albumin level, white blood cell count, and concentrations of PGE2, TGF-β, and IL-10 are important immunological indicators for cancer patients." (PMID 25267108, 2014). "Briefly, previously reported prognostic covariates (lactate dehydrogenase level, serum albumin level, number of metastatic sites, and ECOG performance status) for patients with advanced cancer treated on phase I clinical trials were confirmed in this analysis." (PMID 25313136, 2014). "The independent predictors of cancer included elevated alkaline phosphatase level, elevated LDH level, high white blood cell count, low albumin level, and age >80 years." (PMID 24762986, 2014). "This study suggests that there are four biomarkers in the blood—alpha-1-acid glycoprotein, albumin, VLDL particle size, and citrate—that can be measured by NMR spectroscopy to assess whether otherwise healthy people are at short-term risk of dying from heart disease, cancer, and other illnesses." (PMID 24586121, 2014). "In univariate linear regression analyses, DM, CVD, cancer, dialysis vintage, IDWL, hemoglobin, and serum albumin were correlated with baseline sNa." (PMID 24354674, 2013). "As a result of the preliminary screening by linear regressions and one-way ANOVA, age, α1-AGP, albumin, ALT, body surface area, BW, CLCR, serum creatinine, cancer type, and ECOG performance status were selected as potential covariates." (PMID 22892872, 2013). "It is encouraging that our data suggest albumin and chitosan biodegradable and biocompatible polymer-based HNC to be efficient in inhibiting cancer cells growth as compared to GEM solution as well as negatively charged nanocarriers (M-ANC-G)." (PMID 24106715, 2013). "Particularly, our study demonstrated that combining preoperative serum albumin level, CEA level and UICC stage significantly affect the cancer-specific survival of patients with CRC postoperatively." (PMID 19691850, 2009). "A multivariate analysis identified that low serum albumin level (P = 0.011), advanced UICC stage (P < 0.001), and high carcinoembryonic antigen (CEA) level (P < 0.001) were independent prognostic factors of cancer-specific survival." (PMID 19691850, 2009).
cancer (continued). "A recent example of the impact of nanomedicine in drug delivery is underscored by the success of AbraxaneTM, an albumin nanoparticle conjugate of paclitaxel, and the first FDA-approved anti-cancer agent in this emerging class of drug formulations." (PMID 17439648, 2007). "Tandem alterations in albumin and CRP levels can bolster clinical diagnosis of inflammation and support the predictive power of acute‐phase reactants in the identification of depressive symptoms among cancer patients." (PMID 40851223, 2026). "Albumin-based nutritional indices, such as the CALLY index, HALP score, PNI, and mGPS, have been evaluated in various subjects in the literature; however, their effects on survival in cancer patients have been examined more comprehensively." (PMID 40870500, 2025). "The fibrinogen–albumin ratio (FAR) is a novel inflammatory and nutritional biomarker that has demonstrated prognostic efficiency across diverse cancers, including esophageal cancer, hepatocellular carcinoma, osteosarcoma, non-small-cell lung cancer, and ovarian cancer." (PMID 40650392, 2025). "Significant differences between the two groups were observed in the following variables: age, presence of malignant tumors, SOFA score, red blood cell count, hemoglobin levels, aspartate aminotransferase, potassium, creatinine, BUN, albumin, INR, PT, APTT, and vasopressor use (P < 0.05)." (PMID 41013263, 2025). "Similarly, in our study, we combined CRP with nutritional indicators such as BMI and albumin to create NCR, which has been shown to outperform CRP alone in predicting the prognosis of cancer cachexia." (PMID 40133874, 2025). "ALP and ALB levels are affected by various conditions and factors; therefore, the AAPR is believed to be a more objective index, and its prognostic significance has been investigated in some cancers." (PMID 39941572, 2025). "Fearon consensus criteria, WLGS, NLR, albumin and PNI were routinely collected at ICI initiation in regular clinical practice and predictive of worse disability‐free, hospitalization‐free and overall survival in cancer patients receiving ICI therapy." (PMID 39817619, 2025). "ALB (43.4 vs. 39.2), LYM (1.67 vs. 1.34), RBC (4.42 vs. 4.32), and TBIL (9.2 vs. 7.6) values were found to be significantly higher in cancer patients compared to non-cancer patients." (PMID 40943960, 2025). "Systemic inflammation, reflected in biomarkers like the high-sensitivity C-reactive protein-to-albumin ratio (HAR), fibrinogen (FIB), and hemoglobin (HB), has emerged as a key player in cancer progression, yet its integration into clinical predictive tools remains underexplored." (PMID 41142623, 2025). "Conducted a retrospective analysis on 2,425 white female patients with non-metastatic invasive BC (stage I-III), revealing that low ALB levels were a prognostic factor for reduced survival, independent of cancer stage." (PMID 40896424, 2025). "Thus, even before the onset of cachexia, cancer progression elicited a huge induction of positive-APP production, while albumin expression was reduced." (PMID 40124481, 2025). "Some novel indices that combined nutritional and immunological status indexes have proved their prognostic value in various cancers, such as prognostic nutritional index (PNI), C-reactive protein-albumin-lymphocyte (CALLY), and modified Glasgow prognostic score (mGPS)." (PMID 41211422, 2025). "The integration of serum albumin and ALP levels into a single index provides a more holistic view of the patient’s health status, reflecting both nutritional and inflammatory conditions that are pivotal in cancer progression." (PMID 40741001, 2025). "The administration of a photosensitizer capable of non-covalent binding to albumin in the albumin coating made it possible to provide photoinduced cancer cell death while maintaining minimal dark cytotoxicity." (PMID 40871005, 2025).
cancer (continued). "The Albumin-Myosteatosis Gauge (AMG) proposed for this purpose has previously been studied for its ability to determine prognosis in cancer patients, even in non-breast cancers." (PMID 41002580, 2025). "In these cancers, the ALBI’s albumin component reflects nutritional status, while elevated bilirubin may impair antitumor immunity by suppressing CD4+ T-cell function." (PMID 40722777, 2025). "This work aimed to evaluate two albumin affinity structure-containing peptide-radionuclide conjugate drugs, INER-PP-F11N-1 and INER-PP-F11N-2, for the diagnosis/treatment of cholecystokinin receptor subtype 2 (CCK2R)-overexpressing cancers." (PMID 40724817, 2025). "At the same time, serum albumin, a negative acute phase protein, and considered another promising marker for cancer cachexia remained unchanged in patients with liver metastases but was significantly lower in patients with primary CC." (PMID 41221702, 2025). "The CRP–Albumin–Lymphocyte (CALLY) index is a composite prognostic marker incorporating C-reactive protein (CRP), albumin, and lymphocyte count, reflecting systemic inflammation, nutritional status, and immune function in cancer patients." (PMID 40836295, 2025). "In addition, Hu's group developed an iron death inducer, human serum albumin-iridium oxide (HSA-Ce6-IrO2, HCIr) nanocluster of conjugated Ce6, and used it to achieve iron-like death of cancer cells triggered by SDT." (PMID 39992547, 2025). "The neutrophil‐percentage‐to‐albumin ratio (NPAR) has been used for prognostic assessment in non‐cancerous diseases, but its relationship with mortality risk in cancer patients has not been explored." (PMID 39831739, 2025). "The C-reactive protein-albumin-lymphocyte (CALLY) index represents a novel composite biomarker that integrates three fundamental aspects of cancer pathophysiology: systemic inflammation (CRP), nutritional status (albumin), and immune function (lymphocyte count)." (PMID 41179090, 2025). "Additionally, we have learned that interaction with proteins such as serum albumin (HSA) can enable the compounds to slowly release and extend their lifetime to assist in the delivery of the compounds into cancer tissue." (PMID 39940763, 2025). "Importantly, these data show that albumin-hitchhiking STING agonists are effective against metastases in the lung, one of the most common metastatic sites for many cancers." (PMID 38766114, 2024). "Owing to the surface location of charged groups, which are rich in negative and positive charges, albumin is a versatile protein used to develop innovative drug-delivery systems for cancer therapeutics." (PMID 39456987, 2024). "Here, a TAMs-targeted albumin nanoparticles-based delivery system (M@SINPs) was constructed for the co-delivery of photosensitizer IR820 and SHP2 inhibitor SHP099 to potentiate macrophage-mediated cancer immunotherapy." (PMID 38890636, 2024). "Using the albumin conjugation technique, our group successfully generated several immunomodulatory molecules previously, including Albumin (Alb)-GM-CSF, Alb-IL2, and Alb-IFNβ, for both vaccination and anti-cancer purposes." (PMID 38287325, 2024). "The Kaplan-Meier survival curves revealed that patients with serum albumin levels ≤ 4.2 g/dL experienced a lower overall survival rate compared to those with levels > 4.2 g/dL, regardless of the extent of cancer malignancy." (PMID 38500655, 2024). "Thus, the fibrinogen-to-albumin ratio (FAR) has emerged as a potential biomarker reflecting both inflammatory and nutritional status, including cardiovascular disease and cancer." (PMID 39744304, 2024). "Recently, based on the level of albumin, the novel nutrition assessment tools, named the Prognostic Nutrition Index (PNI) and Naples prognostic score (NPS), have gained increasing popularity in predicting the prognosis of patients with different cancers." (PMID 38509518, 2024).